SIRT3 (sirtuin 3)
Diseases named in the same sentence as SIRT3 in open-access papers (continued):
Sharing a sentence is not in itself a finding about the gene and the disease.
fibrosis (27 papers, 2016 to 2025). the formation of excess fibrous connective tissue in an organ or tissue in a reparative or reactive process. "Such cardiac fibrosis was reduced by catalase overexpression and accentuated by mitochondrial sirtuin SIRT3 deficiency, in transgenic mice." (PMID 29763629, 2018). "Overexpression of Sirt3 attenuates intracellular ROS production, which leads to beneficial effects on inflammation, cellular senescence, and age-associated tissue fibrosis." (PMID 29236713, 2017). "Across a range of experimental fibrosis models, including peritoneal, cardiac, pulmonary, and hepatic fibrosis, SIRT3 consistently act as a central suppressor of fibrotic progression." (PMID 40860195, 2025). "SIRT3 mediated the FOS inhibition through histone H3 deacetylation prevents cardiac fibrosis and inflamm-aging." (PMID 40060963, 2025). "SIRT3 overexpression alleviates cardiac fibrosis by deacetylating STAT3 and reducing the expression of NFATc2." (PMID 37196115, 2023). "In the present study, we explored the role of SIRT3 in cardiac ferroptosis and its contribution to cardiac fibrosis." (PMID 37408261, 2023). "FOS, a gene critical for monocyte and macrophage function, showed that SIRT3-mediated inhibition of FOS through histone H3 deacetylation prevents cardiac fibrosis and inflammation." (PMID 35600966, 2022). "Small molecule sirtuin stimulators that augment SIRT3 (i.e., resveratrol, viniferin, and honokiol) can attenuate bleomycin-induced fibrosis in the lungs, skin, heart, and kidneys." (PMID 34202229, 2021). "We concluded that SIRT3 has a critical role in Ang‐II‐induced cardiac fibrosis and remodelling through pericyte transition and ROS‐TGF‐β1 pathway." (PMID 32463172, 2020). "SIRT3 knockout mice showed cardiac fibrosis and inflammation that was characterized by augmented transcriptional activity of AP-1." (PMID 32296036, 2020). "Overall, our data demonstrated that Ang‐II led to increased cardiac fibrosis partly via regulating SIRT3‐mediated pericyte‐myofibroblast/fibroblast transition and ROS‐TGF‐β1 pathway." (PMID 32463172, 2020). "Resveratrol activates SIRT3, which then ameliorates cardiac fibrosis and improves cardiac function via the transforming growth factor-β/Smad3 pathway." (PMID 27840668, 2016). "However, the activation of SIRT3 can inhibit cardiomyocyte apoptosis and alleviate cardiac fibrosis by reducing ROS, enhancing the activities of antioxidant enzymes such as SOD2, and improving mitochondrial function." (PMID 40943150, 2025). "SIRT3 prevents cardiac fibrosis and inflammation via regulating the FOS/AP-1 pathway." (PMID 37196115, 2023). "Sirtuin3 (SIRT3), a deacetylase, regulates the FOS/AP-1 pathway to alleviate myocardial fibrosis and inflammation." (PMID 40520937, 2025). "The deacetylated, active form of OPA1 corrects cardiac fibrosis and malfunction, OPA1 deacetylation via SIRT3 being the only known post-translational change that activates OPA1." (PMID 34829803, 2021). "In the physiological aging process in mice, 12-week NAC treatment ameliorated aortic fibrosis possibly by stimulating M2 macrophage polarization, and SIRT1, SIRT3 and FOXO1 may play a role in unidentified pathways linking vascular oxidative stress to fibrosis associated with aging." (PMID 34530696, 2021).
Myocardial fibrosis (27 papers, 2018 to 2026). "Cardiac fibroblasts with SIRT3 knockdown and mice with SIRT3 deficiency further verified the protective effect on myocardial fibrosis by H2S via a SIRT3-depended manner." (PMID 34603602, 2021). "We hypothesize that SIRT3 deficiency increases ROS and increases perivascular and myocardial fibrosis, thus resulting in endothelial and myocardial dysfunction." (PMID 30873415, 2019). "EMPA significantly improved cardiac function, reduced myocardial fibrosis, and attenuated ferroptosis, concomitant with upregulated silent information regulator 3 (SIRT3) expression." (PMID 42193166, 2026). "This suggests that exercise inhibits cardiomyocyte apoptosis and ROS production by promoting SIRT3 expression, thereby attenuating myocardial fibrosis." (PMID 40182630, 2025). "The downregulation of SIRT3 weakened the anti-fibrotic ability and promoted the release of cytokines, which in turn aggravated the progression of myocardial fibrosis." (PMID 41414645, 2025). "Although the role of SIRT3 in myocardial fibrosis has been clarified, its effects on upstream and downstream molecules of TGF-β1 still need to be further studied." (PMID 37196115, 2023). "NaHS, an H2S donor, is a potential treatment for transverse aortic constriction (TAC)-induced myocardial fibrosis and Ang II-induced cardiac fibroblast proliferation by enhancing SIRT3 levels." (PMID 37237500, 2023). "Altogether, NaHS attenuated myocardial fibrosis through oxidative stress inhibition via a SIRT3-dependent manner." (PMID 34603602, 2021). "Recent studies demonstrate that SIRT3 knockout mice spontaneously develop myocardial fibrosis, while SIRT3 overexpression partially attenuates the cardiac hypertrophic response by regulating the expression of antioxidant genes and mitochondrial function." (PMID 34776960, 2021). "This was achieved by increasing the level of SIRT3 protein and improving mitochondrial quality control, which in turn led to an improvement in mitochondrial function in cardiomyocytes and a subsequent inhibition of myocardial fibrosis progression." (PMID 40182630, 2025). "Another study demonstrated that swimming exercise for 15 minutes per day, 5 days per week for 8 weeks inhibited myocardial fibrosis, apoptosis, and ROS production, and upregulated Sirtuins3 (SIRT3) expression and antioxidant enzyme SOD2 activity in aged MI mice." (PMID 40182630, 2025). "Furthermore, 2-aminopyridine-4-carboxamide (2-APQC), an activator of SIRT3, significantly attenuates myocardial fibrosis by inhibiting the JNK pathway and enhancing mitochondrial function." (PMID 41150746, 2025). "This suggests that Ang-II-induced myocardial fibrosis may involve both SIRT3-mediated transformation of pericyte into myofibroblast/fibroblasts and ROS-TGF-1 activity." (PMID 38294557, 2024). "SIRT3 plays a vital role in mitochondrial biosynthesis and oxidative stress, which might be critical in the process of myocardial fibrosis." (PMID 34603602, 2021). "Taken together, NaHS alleviated myocardial fibrosis in mice with TAC via a SIRT3-dependent manner." (PMID 34603602, 2021). "Our present study investigates whether hydrogen sulfide (H2S) attenuated myocardial fibrosis and explores the possible role of SIRT3 on the protective effects." (PMID 34603602, 2021). "Therefore, SIRT3 was focused on the possible pathway of the protective effect on myocardial fibrosis next." (PMID 34603602, 2021). "Furthermore, Ang‐II‐induced myocardial fibrosis, capillary rarefaction and cardiomyocyte hypertrophy were accentuated by knockout of SIRT3." (PMID 32463172, 2020). "Disruption of SIRT3-mediated EC metabolism and impairment of angiogenesis may promote cardiomyocyte hypoxia and myocardial fibrosis, leading to diastolic dysfunction and HFpEF." (PMID 30873415, 2019).
Myocardial fibrosis (continued). "Moreover, NaHS equally reduced blood pressure but enhanced the H2S level in all mice, suggesting that the failure of NaHS to inhibit myocardial fibrosis in SIRT3 KO mice is due to SIRT3 deficiency but not blood pressure." (PMID 34603602, 2021). "Therefore, our present study investigates whether H2S attenuated cardiac fibroblast proliferation in vitro and myocardial fibrosis in vivo and explores the possible role of SIRT3 on the protective effects." (PMID 34603602, 2021). "However, the possible role of SIRT3 on the protective effects of H2S against myocardial fibrosis was unknown." (PMID 34603602, 2021). "However, it is not known whether H2S protects against cardiac fibroblast proliferation and myocardial fibrosis via SIRT3 activation." (PMID 34603602, 2021). "A mouse myocardial fibrosis model induced by angiotensin II confirmed that SIRT3 enhanced mitochondrial autophagy, mediated by Pink/Parkin, and attenuated the production of mitochondrial ROS, restored vascular budding and tube formation, and improved myocardial fibrosis and cardiac function." (PMID 29643974, 2018). "At the same time, bulk of classical inflammatory pathways have been proven to contribute to cardiac dysfunction and myocardial fibrosis, such as cGAS-STING, SIRT3-FOS and cAMP-AMPK pathways." (PMID 40623816, 2025). "We found that there was more serious fibrosis in SIRT3 KO mice after TAC, suggesting the protective role of SIRT3 in TAC-induced myocardial fibrosis." (PMID 34603602, 2021). "A study demonstrated that resveratrol activates SIRT3 and downregulates the TGF-β/Smad3 pathway to improve myocardial fibrosis." (PMID 29643974, 2018). "In conclusion, NaHS, a H2S donor, enhanced SIRT3 transcription and decreased the DRP1 level to possibly ameliorate mitochondrial membrane rupture, suppress oxidative stress, and alleviate Ang II-induced cardiac fibroblast proliferation and TAC-induced myocardial fibrosis." (PMID 34603602, 2021). "However, the mechanism of how H2S regulates SIRT3 transcriptional activity during myocardial fibrosis is not known at present and needs to be confirmed in further studies." (PMID 34603602, 2021). "Myocardial fibrosis was also elevated in cardiac tissue of SIRT3 knockout mice, as reported in other studies, and consistent with this, the expression of TGF-β, ATF4, and EDN-1 was inhibited by SIRT3 overexpression in AC16 cells and in neonatal rat cardiomyocytes." (PMID 32296036, 2020).
pulmonary fibrosis (27 papers, 2015 to 2026). Chronic progressive interstitial lung disorder characterized by the replacement of the lung tissue by connective tissue, leading to progressive dyspnea, respiratory failure, or right heart failure. "SIRT3 deficiency promotes lung fibrosis by increasing mitochondrial DNA damage in alveolar epithelial cells leading to apoptosis." (PMID 38245795, 2024). "Deficiency of SIRT3 contributes to increased mitochondrial DNA damage and apoptosis in alveolar epithelial cells, exacerbating the progression of pulmonary fibrosis." (PMID 38294557, 2024). "SIRT3 deficiency promotes lung fibrosis by augmenting alveolar epithelial cell mitochondrial DNA damage and apoptosis." (PMID 37196115, 2023). "SIRT3 deficiency promotes pulmonary fibrosis by enhancing mitochondrial DNA damage and apoptosis in alveolar epithelial cells." (PMID 37483618, 2023). "Despite these limitations, our findings clearly suggest that SIRT3 overexpression can attenuate lung fibrosis following asbestos exposure in association with reduced lung mtDNA damage and recruitment of Mo-AMs." (PMID 34202229, 2021). "Sirt3−/− mice are also more susceptible to bleomycin- and asbestos-induced lung fibrosis in association with detrimentally impacted mtOGG1 function, resulting in mtDNA damage in AECs and fibroblasts." (PMID 34202229, 2021). "Second, we have focused on AECs in these studies while others have investigated how SIRT3 deficiency impacts fibroblast biology necessary for promoting lung fibrosis." (PMID 34202229, 2021). "Mitochondrial SIRT3, a member of sirtuin family has been implicated in the regulation of lung fibrosis development with respect to regulating mtDNA damage via modulating 8-oxoguanine-DNA glycosulase-1 (OGG1) acetylation, a known DNA repair enzyme." (PMID 30386443, 2018). "Sirtuin 3 (SIRT3), a mitochondrial histone deacetylase, has been recognized as an anti-aging gene, and its dysregulation is implicated in the pathophysiological processes of pulmonary fibrosis." (PMID 40008127, 2025). "It has been reported that SIRT3 deficiency promoted pulmonary fibrosis." (PMID 36193088, 2022). "Finally, SIRT3-deficient mice showed an increased susceptibility to pulmonary fibrosis that was related to enhanced canonical TGFβ signaling." (PMID 35268452, 2022). "Accumulating evidence firmly implicates SIRT3 deficiency in the development of pulmonary fibrosis." (PMID 34202229, 2021). "SIRT3 deficient mice showed enhanced lung fibrosis development by bleomycin and asbestos exposure." (PMID 30386443, 2018). "In particular, circulating SIRT1 and SIRT3 were found to be decreased in patients with dcSSc in respect to patients with lcSSc, and showed an association with the extent of skin involvement (i.e., mRSS), the presence of lung fibrosis on HRCT scan of the chest, and worse pulmonary function." (PMID 35268452, 2022). "However, studies are needed in the future to determine whether activation of SIRT3 would be sufficient to prevent cardiac and pulmonary fibrosis associated with aging." (PMID 31011489, 2019). "Further, downregulation of SIRT3 expression enhances the stability of FoxM1, thereby accelerating bleomycin-induced pulmonary fibrosis through the activation of pulmonary fibroblasts." (PMID 41797045, 2026).
pulmonary fibrosis (continued). "This suggested that the PGC1-alpha/Sirt3 pathway mediates the inhibitory effect of hirudin on fibroblast senescence-induced pulmonary fibrosis and anti-oxidative stress." (PMID 39062010, 2024). "This study is the first to demonstrate that hirudin inhibits fibroblast senescence by exerting an anti-oxidative stress effect through activation of the PGC1-alpha/Sirt3 pathway, thereby suppressing pulmonary fibrosis." (PMID 39062010, 2024). "This was considered due to the significant elevation in PGC1-alpha and Sirt3 expression levels in the lung tissues of mice with pulmonary fibrosis upon hirudin treatment, and the important role of the PGC1-alpha/Sirt3 pathway in senescence." (PMID 39062010, 2024). "Whole-body overexpression of SIRT3 protects mice from asbestos-induced pulmonary fibrosis by mitigating lung mtDNA damage." (PMID 38245795, 2024). "We observed that hirudin significantly raised the expression levels of PGC1-alpha and Sirt3 in pulmonary fibrosis mouse lung tissues." (PMID 39062010, 2024). "In summary, hirudin inhibited fibroblast senescence through activation of the PGC1-alpha/Sirt3 pathway, which in turn exerted its anti-pulmonary fibrosis effect." (PMID 39062010, 2024). "Hirudin inhibited fibroblast senescence by activating the PGC1-alpha/Sirt3 pathway through promoting the expression of PGC1-alpha and Sirt3; that is the specific mechanism by which it exerts its anti-pulmonary fibrosis effect." (PMID 39062010, 2024). "Conversely, silencing of SIRT3 promotes these detrimental effects, ultimately leading to pulmonary fibrosis." (PMID 38294557, 2024). "Among them, Sirt3 has been demonstrated to exert an anti-pulmonary fibrosis effect by inhibiting fibroblast senescence." (PMID 39062010, 2024). "Sirtuin 3 (Sirt3) siRNA (50 μg) was injected through the tail vein once a week for 2 weeks to explore its effect on the anti-pulmonary fibrosis of baicalein." (PMID 36815239, 2023). "SIRT3 overexpression ameliorates asbestos-induced pulmonary fibrosis, mt-DNA damage, and lung fibrogenic monocyte recruitment." (PMID 37196115, 2023). "Our findings suggested that the dysregulation of Sirt3-mediated pulmonary fibroblast senescence contributed to BLM-induced lung fibrosis, and Sirt3 knockdown blocked the protective role of baicalein in preventing BLM-induced fibrosis." (PMID 36815239, 2023). "SIRT3 blocks myofibroblast differentiation and pulmonary fibrosis by preventing mitochondrial DNA damage." (PMID 37196115, 2023). "Baicalein restored the BLM-induced downregulation of Sirt3 expression in lung tissues and silencing of Sirt3 abolished the inhibitory role of baicalein against BLM-induced lung fibrosis, fibroblast senescence and activation of TGF-β1/Smad signalling pathway." (PMID 36815239, 2023). "Next, the impact of Sirt3 siRNA on the protective role of baicalein against BLM-induced pulmonary fibrosis was explored." (PMID 36815239, 2023). "SIRT3 has a protective role in various inflammatory and fibrotic processes, including kidney injury, cardiomyopathy, and pulmonary fibrosis, and regulates inflammasome activation in various model systems." (PMID 35215060, 2022). "Our results are in line with previous studies reporting that both SIRT1 and SIRT3 are important regulators of lung fibrosis, as they are able to attenuate TGFβ-mediated profibrotic responses both in vitro and in vivo." (PMID 35268452, 2022). "A significant decrease in SIRT3 levels were finally reported in lung tissue from SSc patients, as well as in two murine models of pulmonary fibrosis." (PMID 35268452, 2022).